HLA-C (major histocompatibility complex, class I, C)
Diseases named in the same sentence as HLA-C in open-access papers (continued):
Sharing a sentence is not in itself a finding about the gene and the disease.
Crohn disease (22 papers, 2008 to 2026). A gastrointestinal disorder characterized by chronic inflammation involving all layers of the intestinal wall, noncaseating granulomas affecting the intestinal wall and regional lymph nodes, and transmural fibrosis. "A meta-analysis found that rs735316 (AA) was associated with an increased risk of Crohn’s disease by lowering miR-148 expression and subsequently HLA-C expression in individuals with intact miR-148 binding sites located in HLA-C." (PMID 39355248, 2024). "Notably, high HLA-C expression has a deleterious effect by conferring risk for Crohn’s disease." (PMID 28449694, 2017). "Low miRNA-148 levels and high HLA-C levels are associated with better control of HIV, but a higher risk of Crohn’s disease." (PMID 39355248, 2024). "(2013) also found that the 3’UTR of HLA-C contains binding sites for miR-148, resulting in lower HLA-C expression in individuals with Crohn’s disease." (PMID 39355248, 2024). "The association was fine-mapped to a population-specific HLA haplotype of HLA-C*12:02–HLA-B*52:01–HLA-DRB1*15:02, which is previously reported to increase the risk of ulcerative colitis and decrease the risk of Crohn’s disease." (PMID 39019884, 2024). "In other clinical settings, a high HLA-C expression was correlated to more efficient recognition of HIV by cytotoxic cells and lower viremia in patients, while lower levels of HLA-C expression had a protective effect from Crohn’s disease." (PMID 35666741, 2022). "In a cohort of 2650 Crohn’s disease cases, HLA-B*08:01 and HLA-C*07:01 (which are in tight linkage disequilibrium with each other and with the class II genes of the haplotype) but not HLA-A*01:01 were significantly associated with good prognosis." (PMID 32238263, 2020). "Alternatively, lower HLA-C expression is protective in Crohn’s disease, suggesting a key role for HLA-C in the presentation of immunogenic antigens that participate in autoimmunity." (PMID 28529723, 2017). "Individuals with HLA-C*01:02:01 may have an increased level of HLA-C expression, which is disadvantageous in inflammatory diseases such as Crohn’s disease." (PMID 37958966, 2023). "We note that the association at HLA-C showed the most significant signal when we performed the analysis with all the available control individuals (i.e., the controls with a known history of ulcerative colitis or Crohn’s disease were not explicitly excluded)." (PMID 39019884, 2024). "While high HLA-C expression increases the presentation of viral antigens to cytotoxic T cells and viral clearance, it could also lead to inappropriate activation of T cells, contributing to chronic inflammation in the gastrointestinal tract leading to Crohn’s disease." (PMID 39355248, 2024). "(2013) showed that HLA-C expression had opposing effects on HIV and Crohn’s disease." (PMID 39355248, 2024).
Arthritis (21 papers, 2005 to 2024). Inflammation of a joint. "In our patients with PC and PCV-undifferentiated arthritis, HLA DRB1*01-B1*011 and C*06–C*07, haplotypes usually correlated with early arthritis and were adequately represented with a predominance of HLADRB1*11 and HLAC*07." (PMID 38137631, 2023).
asthma (20 papers, 2007 to 2025). "Within HLA-C, threonine residue at position 73 and alanine residue at position 90 were associated with increased odds of being an asthma case (OR = 1.40, 95%CI: 1.13 to 1.74; OR = 1.44, 95%CI: 1.16 to 1.79, respectively)." (PMID 37415598, 2023). "For Black participants, threonine residue at position 73 within HLA-C was associated with a 126% increase in the odds of being an asthma case." (PMID 37415598, 2023). "The risk amino acid (alanine) is on HLA-C*02, *03, *05, *06, *07, *08, *12, *15, *16, *17, and *18 alleles in this sample (including rare alleles), and the amino acid (serine) that is associated with decreased risk of asthma is on HLA-C*01:02, *04:01, *04:07, *14:02, and *14:03 alleles." (PMID 35606880, 2022). "For the HLA analysis, HLA-B*40:02 and HLA-DRB1*04:05, HLA-B*40:02, HLA-C*04:01, and HLA-DRB1*04:05, and HLA-DRB1*03:01 and HLA-DQB1 were significantly associated with late-onset asthma in all, White, and Black participants." (PMID 37415598, 2023). "For White participants, two MHC class I alleles, HLA-B*40:02 and HLA-C*04:01, and one MHC class II allele, HLA-DRB1*04:05, were significantly associated with late-onset asthma." (PMID 37415598, 2023). "HLA-C*04:01 was protective for being a late-onset asthma case (OR = 0.25, 95%CI: 0.09 to 0.70) whereas HLA-B*40:02 and HLA-DRB1*04:05 increased the odds of being a case [(OR = 3.77, 95%CI: 1.91 to 7.44; OR = 8.19, 95%CI: 2.51 to 26.79), respectively]." (PMID 37415598, 2023).
psoriatic arthritis (19 papers, 2006 to 2025). Joint inflammation associated with psoriasis. "HLA-Cw6, HLA-C*12, HLA-C*06, and HLA-C*06:02 were also confirmed as risk factors for Psoriatic Arthritis in various populations." (PMID 38892265, 2024). "HLA-C*01:02 is associated with psoriatic arthritis in the population of southern Han Chinese patients." (PMID 37958966, 2023). "Several of those have been implicated in pro-inflammatory processes; for example, HLA-C has been associated with RA; RNF182 was previously reported to be over-expressed in RA, and TUBB2A was found to be over-expressed in psoriatic arthritis." (PMID 33461591, 2021). "This study established that HLA-C*06:02-negative patients were more likely to respond to adalimumab than to ustekinumab treatment (most strongly at 6 months), mainly if they also presented psoriatic arthritis." (PMID 33419370, 2020). "Independent of HLA-B and HLA-C, the MICA-129Met allele, especially Met/Met homozygosity, had a strong correlation with the two types of cutaneous psoriasis (PsC) and psoriatic arthritis (PsA)." (PMID 38474281, 2024). "These correlations were not driven by any clinical covariate previously associated with response to adalimumab such as age, gender, ethnicity, smoking, weight, psoriatic arthritis, being biologic naive, the baseline PASI or the presence of the HLA-C*06:02 allele." (PMID 34362923, 2021).
cervical carcinoma (18 papers, 1993 to 2023). A carcinoma arising from either the exocervical squamous epithelium or the endocervical glandular epithelium. "Among the downregulated MHC-I genes that have been found in cervical cancer are human leukocyte antigen (HLA) A, HLA-B, HLA-C, HLA-E, and HLA g." (PMID 36831674, 2023). "HPV+ cervical cancer cells maintain NK cell inhibition via HLA-C/KIR2DL2 and HLA-C/KIR2DL3 interactions." (PMID 35174079, 2022). "HLA-C group 1 was significantly more transmitted with invasive cervical cancer." (PMID 35053153, 2021). "Therefore, we hypothesized that targeting the HLA-C/KIR interaction with lirilumab may represent another novel immunotherapeutic strategy for HPV+ cervical cancer." (PMID 35174079, 2022). "Remarkably, expression of HLA‐A, HLA‐B, and HLA‐C was significantly lower in NEC‐GYN compared to ovarian and cervical cancer (P‐value < 0.0001), further corroborating immunosuppressive nature of NEC‐GYN." (PMID 34245124, 2021). "We analyzed the Illumina HiSeq RNA expression data from the TCGA head & neck squamous cell carcinoma (HNSC) and cervical carcinoma (CESC) cohorts for expression of HLA-A, HLA-B, and HLA-C, the three classical genes." (PMID 28891951, 2017). "As HPV+ invasive cervical cancer patients display upregulation in HLA-C/KIR2DL2 and HLA-C/KIR2DL3 antigen pairs, enhancing the HLA-C/KIR interaction may suppress normal NK cell function in HPV+ cervical cancer patients." (PMID 35174079, 2022).
parasite infection (18 papers, 2006 to 2025). "The association of HLA-C*06:02 and HLA-B*53:01 with a higher risk of parasitemia could reflect greater KIR-mediated inhibition leading to dampened cellular immunity at pre-erythrocytic stages or an attenuated clearance of parasites via antibody dependent cellular cytotoxicity." (PMID 33815410, 2021). "Conversely, HLA-C*07:01, a member of the HLA-C1 ligand group which mediates a weaker inhibitory signal via KIR2DL2/3, was associated with lower odds of parasitemia." (PMID 33815410, 2021). "In addition, individuals positive for HLA-C*06:02 (prevalence = 29%) had 1.37 times higher odds of parasitemia compared to those without this allele (p < 0.01, p* < 0.01, q = 0.02)." (PMID 33815410, 2021). "The interaction of HLA-C*06:02 with the strongly inhibitory receptor KIR2DL1 likely influences NK cell education even in the absence of infection, leading to more potent NK cell function upon activation, although it is not evident how this would result in an increased risk of parasitemia." (PMID 33815410, 2021).
colorectal cancer (16 papers, 2003 to 2026). A primary or metastatic malignant neoplasm that affects the colon or rectum. "Based on the study of the immunologic subclassification of colorectal cancers with high microsatellite instability, the decrease in TILs is partly attributed to the downregulation of HLA-A, HLA-B, and HLA-C." (PMID 37190307, 2023). "The differential expression of HLA-C in CRC cells was further validated via microarray analysis of 123 colorectal cancer tissue samples and 25 normal colorectal tissue samples available from NCBI GEO datasets (GEO Accession Number: GSE21510)." (PMID 35379174, 2022). "Further, in only one of the HLA, HLA-C*12:03, we found one potential neoepitope that is shared between these two colorectal cancers." (PMID 32699259, 2020). "Also, in this population, it was recently found that overexpression of HLA-C decreases the cell viability of colorectal cancer, exerting a strong influence on distinct cancer pathways such as JAK/STAT, retinoblastoma and Hedgehog signalling." (PMID 37465164, 2023). "For example, it has been shown that there is a significant decrease in immune activity in colorectal cancer due to a reduced expression of HLA-C in the tumor that did not present genetic structural alterations but rather epigenetic modifications." (PMID 37465164, 2023). "The present immunohistochemical study of colorectal carcinoma lesions with the MEM-E/02 antibody reveals that high expression of HLA-E significantly correlates with high expression of HLA-A, but not HLA-B or HLA-C." (PMID 22032294, 2011).
influenza (16 papers, 2011 to 2024). An acute viral infection of the respiratory tract, occurring in isolated cases, in epidemics, or in pandemics; it is caused by serologically different strains of viruses (influenzaviruses) designated A, B, and C, has a 3-day incubation period, and usually lasts for 3 to 10 days. "While the role of HLA-C in viral respiratory illness remains poorly understood, specific HLA-C alleles are associated with differential risk of infection and/or prognosis in influenza, chikungunya, dengue, lassa, and ebola viruses." (PMID 39337964, 2024). "Due to the use of the pan-class I antibody W6/32 for HLA I isolation, influenza peptides with the capacity to bind HLA-B*35:03 and HLA-C*04:01 were also observed, as well as peptides with predicted capacity to bind more than one of the expressed HLA." (PMID 35255101, 2022). "Specifically, influenza samples maintained higher levels of type I IFN response–associated antiviral ISGs (e.g., IFITM1, IFITM2, IFITM3, OAS2, OAS3, OASL) and antigen presentation genes (e.g., HLA-DRB5, HLA-C, B2M, HLA-B, HLA-E)." (PMID 34618691, 2021). "For instance, HLA-C*05:01 expression may be downregulated in influenza infection." (PMID 39336433, 2024). "One was a proinsulin specific beta chain, found in CD4+ T cells in our study but reported to recognize influenza in a HLA-A*0201 restricted fashion (found in both McPAS and VDJDB) and CMV with a HLA-C*07:02 restriction." (PMID 37908349, 2023). "Some of our observed influenza immunopeptides did not match with any allotype or were assigned to HLA-C, but with low predicted affinity." (PMID 35051231, 2022). "Although not statistically significant, a higher prevalence of HLA-C*03:02 (3.98% in the influenza positive group compared to 1% in the influenza contact group) was observed in the Mexican IAV H1N1/09 patient group." (PMID 36423187, 2022).
sarcoidosis (15 papers, 2009 to 2025). Sarcoidosis is a multisystemic disorder of unknown cause characterized by the formation of immune granulomas in involved organs. "As a protective factor and a risk factor, HLA-C*03:02 and HLA-C*03:04 were associated with sarcoidosis in Koreans, respectively." (PMID 35661780, 2022). "HLA-C*05:01 was associated with sarcoidosis at a primary level as a risk variant." (PMID 35661780, 2022). "Regarding clinical phenotypes of sarcoidosis, HLA-A*01:01, HLA-B*08:01, HLA-C*07:01, HLA-DRB1*03:01, HLA-DQA1*05:01, and HLA-DQB1*02:01 associated with Löfgren’s syndrome." (PMID 37153085, 2023). "Variants previously associated with sarcoidosis risk (HLA-C*03:04, HLA-DRB1*12:01, HLA-DRB1*14:54) and a known protective variant HLA-DPB1*04:01, were associated with sarcoidosis in Koreans." (PMID 35661780, 2022). "Our eQTL/GWAS results implicating MHC Class I and II genes are quite consistent with prior candidate gene/GWAS sarcoidosis studies as we identified MHC Class I genes HLA-B and HLA-C to be well represented in EAs (compared to controls) and HLA-B primarily in AAs." (PMID 38390497, 2023).
vitiligo (15 papers, 2011 to 2025). Generalized well circumscribed patches of leukoderma that are generally distributed over symmetric body locations and is due to autoimmune destruction of melanocytes. "Our study reaffirms previous reports linking HLA‐A, HLA‐C, and HLA‐DRB1 to vitiligo, and further validates the association of HLA‐C with freckles." (PMID 40657813, 2025). "The DDR1 gene is located between the HLA-E and HLA-C genes at chromosomal region 6p21, previously linked to vitiligo susceptibility in a Chinese population." (PMID 24385829, 2013). "In the four regression models we built, two loci in HLA-C/HLA-B and HLA-DQA2 consistently appear in all models, and more importantly, rs9468925 in HLA-C/HLA-B is reported as the top association signal in a GWAS of vitiligo in the same population of study." (PMID 22125590, 2011). "Similar to vitiligo, these mutations are distributed in HLA‐A, HLA‐B, HLA‐C, HLA‐DQB1, and so on." (PMID 40657813, 2025). "Similar to previous studies, our findings suggest that mutations in the MHC region of vitiligo exist in multiple HLA genes, including but not limited to HLA‐A, HLA‐DRB1, HLA‐B, HLA‐C, and so on." (PMID 40657813, 2025). "Using Beagle 4.1, we successfully imputed the SNV, CNV, two–digit and four–digit alleles of HLA genes (HLA-A, HLA-B, HLA-C, HLA-DQA1, HLA-DQB1, HLA-DPA1, HLA-DPB1, HLA-DRB1) and amino acids of 2810 vitiligo subjects (1117 cases, 1693 controls) and 2739 SLE subjects (1,693 controls and 1,046 cases)." (PMID 35082778, 2021).
glioblastoma (12 papers, 2009 to 2025). The most malignant astrocytic tumor (WHO grade IV). "Recently it was found that a decrease in the frequency of HLA-C*08:01 and an increase in HLA-C*04:01 is associated in the Korean population with the risk of generating glioblastoma." (PMID 37465164, 2023). "In a previous study, several HLA-B and HLA-C alleles and haplotypes were positively or negatively associated with the occurrence and prognosis of glioblastoma multiforme (GBM)." (PMID 19774073, 2009). "2Cαβ-cTCR-transduced T cells additionally recognized the glioblastoma cell line MZ-222-GBM/HLA-C*07:01 and the endogenously HLA-C*07:01+ glioblastoma cell line MZ-483-GBM." (PMID 37849763, 2023).
leprosy (12 papers, 2015 to 2022). Leprosy is a chronic infectious disease affecting primarily the skin and peripheral nervous system. "Our team previously used the Han-MHC database as a reference panel for fine mapping and identified four independent sites associated with leprosy (HLA-DRβ1 amino acid Tyr26, HLA-C*08:01, HLA-DQA1*03:03)." (PMID 34976012, 2021). "In our conditioning analysis we were unable to dissociate the protection signal for CDSN/PSORS1C2 amino acid changes from our previously reported HLA-C*07:06 association with leprosy." (PMID 34879060, 2021). "HLA fine mapping showed the HLA-C*07:06 allele to be associated with leprosy protection with a similar frequency and the same direction of association as the CDSN–PSORS1C2 amino acid changes." (PMID 34879060, 2021). "In the Chinese HLA imputation-based meta-analysis, HLA-C*08:01 and specific HLA-C amino acids were found to be independent protective and risk factors for leprosy." (PMID 32421744, 2020). "The leprosy protective signal #2 is dominated by alleles that are part of a HLA-C*07:06 ~ HLA-B*44:03 ~ HLA-DRB1*07:01 haplotype." (PMID 32776973, 2020). "The univariable borderline association of HLA-DRB1*07:01 with leprosy was fully explained by HLA-C*07:06/HLA-B*44:03 by multivariable analysis." (PMID 32776973, 2020). "Employing samples from Vietnam and North India, SNPs in the HLA class I region were found associated with leprosy per se and strongly implicated the HLA-C*15:05 allele in leprosy susceptibility." (PMID 30116885, 2018). "In B leprosy patients, we observed decreased frequencies for these 2 alleles (5.94% for HLA-C*05 and 16.34% for HLA-DRB1*07)." (PMID 25605482, 2015). "This residue was correlated with one of the HLA-C*15 alleles that have been suggested to be associated with Kawasaki disease, Behçet’s disease, and leprosy." (PMID 26613595, 2015). "HLA-C*12 was previously shown to be associated with susceptibility to leprosy per se in a population in Southeast Brazil; however, no study has shown an association between HLA-B*58 and leprosy." (PMID 25605482, 2015). "In addition, haplotypes containing HLA-DRB3~ HLA-DRB1*12:02 and HLA-C*07:06~ HLA-B*44:03~ HLA-DRB1*07:01 alleles were found as two independent protective factors for leprosy." (PMID 32776973, 2020). "In addition to HLA-DRB1, variants in HLA-DQA1 and HLA-C were also associated with leprosy in the Chinese population." (PMID 32776973, 2020). "Killer immunoglobin-like receptors genes—KIR2DS1, 2DS2, and 3DS1—and their HLA ligands were associated with leprosy in a Brazilian population and HLA-C, a classical ligand for KIRs, was observed as a risk factor for leprosy in Vietnamese family based and Indian case-control populations." (PMID 30079069, 2018). "HLA-B*49 and HLA-C*05 were also associated with protection against B leprosy." (PMID 25605482, 2015). "The case-controlled analysis results showed a significant association between B leprosy and HLA-C*05 (5.94% vs. 14.02%; p = 0.002, OR = 0.38, 95% CI = 0.20–0.73, pc = 0.032) and HLA-DRB1*07 (16.34% vs. 26.77%; p = 0.003, OR = 0.53, 95% CI = 0.3–0.8, pc = 0.039)." (PMID 25605482, 2015). "For this, we adjusted each of the formally non-significant HLA alleles on the presence of HLA-DQA1*01:05, HLA-C*07:06 and HLA-DRB1*12 and identified seven HLA four-digit alleles with evidence (Pconditional < 0.01) for association with leprosy." (PMID 32776973, 2020). "The rs114598080 SNP, located in a CTCF binding site (ENSR00000262841) 15.6 kb upstream of the HLA-C gene, gave a univariate p-value of 8.8x10-13 in the combined analysis, with an OR for developing leprosy for AG vs. GG (or AA vs. AG) of 1.47 [1.46–1.48]." (PMID 32421744, 2020). "HLA-B*53 (6.43% vs. 2.93%; p = 0.050, OR = 2.28, 95% CI = 1.05–4.94, pc =1.60) and HLA-C*16 (10.4% vs. 5.44%; p = 0.030, OR = 2.02, 95% CI = 1.10–3.67, pc = 0.48) were also more frequent in B leprosy patients than in healthy controls." (PMID 25605482, 2015).